SOX2 (SRY-box transcription factor 2)
Diseases named in the same sentence as SOX2 in open-access papers (continued):
Sharing a sentence is not in itself a finding about the gene and the disease.
cervical cancer (continued). "The stem cell-related transcription factors, including SOX2, Oct4, and Nanog, were decreased in UBE2T-silenced cells and increased in UBE2T-overexpressed cells, revealing that cervical cancer stem cell traits were promoted by UBE2T." (PMID 34703898, 2021). "Meanwhile, SOX2 has been previously identified as the key factor in several types of CSC,36, 37 including cervical cancer." (PMID 32954681, 2020). "Together, our data demonstrated that NF‐YA was highly expressed in cervical cancer and promoted the cell proliferation, tumorigenicity and CSC characteristic by trans‐activating the expression of SOX2." (PMID 32954681, 2020). "To determine the function of these genes in human cervical cancer, we examined the expression of DEC1, DEC2, SOX2 and c-MYC in human cervical cancer tissues." (PMID 33089188, 2020). "In conclusion, NF‐YA highly expressed in cervical cancer, promoted the cell growth in vitro and in vivo and maintained the cervical CSC characteristics by driving SOX2 expression." (PMID 32954681, 2020). "Several markers, such as Oct4, ABCG2, ALDH1, SOX2 and CD49f, were identified as CCSC-specific markers in cervical cancer cell lines." (PMID 31572058, 2019). "The expression of OCT4, SOX2, and NANOG in cancer stem cell-enriched cultures of HeLa, SiHa, and CaSki cell lines from cervical cancer was higher than their conventional cultures in monolayer." (PMID 31885625, 2019). "While the EGF pathway promotes CSC formation in cervical cancer by inducing SOX2, miR-181a-2-3p/let-7i-5p counteracts the EGF pathway by inhibiting SOX2, thereby reducing the CSC population." (PMID 29777148, 2018). "The expressions of P16INK4A, SOX2, and ALDH1A1 were performed by immunohistochemical staining of tumor samples from 139 cervical cancer patients with International Federation of Gynecology and Obstetrics stages Ib to IV." (PMID 30150594, 2018). "A previous report demonstrated that knockdown of STAT3 protein in cervical carcinoma cell line by siRNA reduced mRNA and protein expressions of NANOG and SOX2." (PMID 29963272, 2018). "Several markers, such as ABCG2, ALDH1, CD133, CD49f and SOX2, were identified as CCSC-specific markers in well-known cervical cancer cell lines based on their stem-like functional probabilities in vitro." (PMID 27343550, 2017). "Comparable to SEC62, SOX2 was amplified and overexpressed in different cancers, e.g., HNSCC, esophageal cancer, cervical cancer and lung cancer." (PMID 28002801, 2017). "To investigate the potential roles of CSC markers in the development of cervical cancer, we determined the expression of Msi1, ALDH1, Sox2 and CD49f in 179 paraffin-embedded cervical carcinoma samples by immunohistochemistry." (PMID 26499463, 2015). "To examine the prognostic value of CSCs markers in cervical cancer, we evaluated the correlation between Msi1, ALDH1, Sox2 and CD49f expression and prognosis in CSCC patients." (PMID 26499463, 2015). "In our study, expression of SOX2 by CTCs of patients with vulvar or cervical cancer was detectable; however, SOX2 expression on CTCs was not enhanced by radio- or chemoradiotherapy." (PMID 40083005, 2025). "Lymph node metastatic cervical cancer cells utilize FAO-derived acetyl Co-A to increase histone H3K27 acetylation at the promoters of stemness genes, as well as enhance the expression of pluripotency-related transcription factors (SOX2, OCT4, and NANOG) and the cervical cancer stem cell marker CD44." (PMID 41219902, 2025). "Mechanistically, whether SOX2 had a regulatory effect on DDR1 transcription and whether GRB2 mediated DDR1 function in cervical cancer were explored." (PMID 39567474, 2024). "In cervical cancer, compared to SOX2-negative cells, tumor cells that endogenously express SOX2 exhibit an enhanced stemness phenotype along with decreased expression of E-cadherin and Vimentin and a high degree of invasive metastatic capacity." (PMID 37213675, 2023).
cervical cancer (continued). "In addition, ACTL6A co-expressed several important genes in the cervical cancer 3q amplicon, including PIK3CA, SOX2 and TP63." (PMID 34395295, 2021). "Upregulation of SOX2 and OCT4A indicates radiation resistance in cervical cancer cells." (PMID 34765546, 2021). "Here, LGR6 is positively correlated with the expression of SOX2 and OCT4, which reveals that multiple genes form a stem cell network to regulate the characteristics of CCSCs and affect the progression and prognosis of cervical cancer." (PMID 34489551, 2021). "Furthermore, the upregulation of CTNNB1, MYC, SOX2, and OCT4 in LGR6high cervical cancer cells was further validated by the RT-PCR assay in vitro." (PMID 34489551, 2021). "Collectively, DEC1, DEC2, SOX2 and c-MYC play important roles of cervical cancer progression." (PMID 33089188, 2020). "We analyzed their expression using RT-qPCR and found that OCT4, SOX2, and NANOG are overexpressed in CSC-enriched sphere cultures as compared with same cell lines grown under adherent conditions from HeLa and SiHa cell lines derived from cervical cancer." (PMID 31885625, 2019). "Additionally, the markers of cervical cancer stem cells (CCSCs) have been accumulating including CD133, CD44, sex determining region Y-box 2 (SOX2), Aldehyde dehydrogenase 1 (ALDH 1), and so on." (PMID 30150594, 2018). "We aimed to investigate the expression and clinical significance of cyclin-dependent kinase inhibitor 2A (P16INK4A), sex determining region Y-box 2 (SOX2), and Aldehyde dehydrogenase 1 family, member A1 (ALDH1A1) in cervical cancer treated with radiotherapy and cervical cell line models." (PMID 30150594, 2018). "Since EGF receptor is frequently over expressed in cervical cancer, we hypothesized that EGF pathway may be responsible for the upregulation of SOX2." (PMID 29777148, 2018). "A pSox2/EGFP system was used to separate the Sox2-positive and the Sox2-negative cells from cervical cancer cell lines, SiHa and C33A cells." (PMID 24489842, 2014). "According to Ravindresh Chhabra’s study, Let-7i-5p overexpression and SOX2 silencing could both decrease the number of spheroids formed in the cervical cancer cell lines HeLa and CaSki, while HMGA2 and SOX2 expression were significantly reduced in CaSki following Let-7i-5p overexpression." (PMID 37829341, 2023). "The stem cell-related transcription factors, including SOX2, Oct4, and Nanog, were decreased in UBE2T-silenced HeLa cells in this study, suggesting that knockdown of UBE2T might suppress the stem cell-like features in cervical cancer." (PMID 34703898, 2021). "HPV-driven cancers of the cervix, head and neck, and penis share copy number alteration sites, most notably copy number gains in 3q, which in addition to PIK3CA contains the telomerase RNA component (TERC), MDS1 and EVI1 complex locus (MECOM), SRY-box 2 (SOX2), and TP63 genes." (PMID 28771191, 2017). "We analyzed SEC62 and SOX2 expression in tissue specimens from 65 HNSCC patients and 29 patients with cervical cancer of unknown primary (CUP); a higher SEC62 and lower SOX2 expression was observed in the lymph node metastases from HNSCC patients compared with the respective primary tumor." (PMID 28002801, 2017). "Furthermore, Sox2 staining was detected in the majority of tumor sphere cells isolated from fresh cervical cancer tissues but not from the differentiated cells." (PMID 22284662, 2012). "However, only Sox2-negative cells could be detected in the tumor tissues formed by the Sox2-negative cervical cancer cells." (PMID 24489842, 2014). "The level of expression of OCT4, SOX2, KLF4, C-MYC, and NANOG (OSKM-N) proteins was higher in cervical cancer (CC) samples than in a nontumor sample." (PMID 31885625, 2019). "Also, overexpression of FAP1-AS1 had no statistical impact on cervical cancer cell stemness, as shown by no statistical difference in the level of NANOG and SOX2 between the control group and the overexpressed AFAP1-AS1 group." (PMID 39574469, 2024).
cervical cancer (continued). "For CCSC enrichment, the human cervical cancer cell line SiHa was grown as non-adherent cells in stem cell-conditioned media (cervospheres) and characterised using sphere formation assay and flow cytometric analysis of stemness markers CD49f, CK17, Sox2, Nanog, and Oct4." (PMID 42077252, 2025).
esophageal squamous cell carcinoma (68 papers, 2013 to 2025). Esophageal squamous cell carcinoma (ESCC) is a type of esophageal carcinoma (EC) that can affect any part of the esophagus, but is usually located in the upper or middle third. "Sox2 similarly associates with the 1000+ bp site in select cancer cell populations such as thyroid gland medullary carcinoma and esophageal SCC The third site at ~ 68,000 bp downstream of the TSS is bound by Sox2 in ESCs and iPSCs." (PMID 31610800, 2019). "For example, in esophageal squamous cell carcinoma, SOX2 promoter hypermethylation seemed to have caused SOX2 silencing and the loss of SOX2 expression was associated with poor prognostic outcome." (PMID 30867047, 2019). "The transcription factor SOX2 has been identified as an amplified lineage-survival oncogene in lung and esophageal SCC, and its overexpression has been shown to be associated with better prognosis." (PMID 25586059, 2015). "Namely, SOX2 can promote esophageal squamous cell carcinoma as it is commonly amplified in esophageal squamous cell carcinomas and capable of driving cancer in overexpression mouse models." (PMID 40587339, 2025). "Underpinning these dynamics, AKT assumed a pivotal role in preserving SOX2 stability across diverse esophageal squamous cell carcinoma cell lines." (PMID 40034124, 2025). "For example, YBX1 interacts with SOX2 mRNA to enhance its stability in esophageal squamous cell carcinoma." (PMID 40703976, 2025). "We previously reported that suppression of ΔNp63 and SOX2 is effective in inhibiting lung and esophageal SCC growth." (PMID 40871074, 2025). "Recently, peptide aptamer targeting SOX2 displayed inhibition of proliferation and migration of esophageal SCC." (PMID 35055392, 2022). "A previous study revealed that WWC1 overexpression hindered the SOX2-induced migration ability and invasive potential in esophageal squamous cell carcinoma." (PMID 36158126, 2022). "Our results were consistent with previous reports on the amplification of SOX2 and the characterization of its role as an oncogene in lung and esophageal SCC." (PMID 32130794, 2020). "SOX2 was shown to be overexpressed in esophageal cancer and inhibiting AKT stabilizes SOX2 expression in esophageal squamous cell carcinomas." (PMID 32867711, 2020). "SOX2 is shown to be an amplified lineage survival oncogene in lung and esophageal squamous cell carcinomas." (PMID 32092088, 2020). "TF SOX2 is a part of the core regulatory network that determines chromatin accessibility, epigenetic modification and gene expression patterns in esophageal squamous cell carcinoma cell lines." (PMID 35134148, 2020). "In the past, SOX2 was identified as a novel lineage survival oncogene in lung and esophageal SCC, and numerous experimental data support the assumption that SOX2 promotes cell motility, proliferation and invasive capacity of cancer cells." (PMID 29596469, 2018). "We then determined SOX2 and CDKN1A expression in lung and esophageal SCC cells after Ad-shSOX2 or Ad-ATF/SOX2 infection." (PMID 29262545, 2017). "More recently, SOX2 has been identified as a lineage-survival oncogene in lung and esophageal SCC and recurrent copy number gain of chromosome 3q26; the gene locus encoding SOX2 represents a frequent alteration in HNSCC." (PMID 28671620, 2017). "Recently, SOX2 was identified as a lineage specific oncogene, recurrently amplified and activated in lung and esophageal squamous cell carcinoma (SCC)." (PMID 29262545, 2017). "SOX2 is a candidate oncogene present in this locus and amplification of SOX2 has been reported in lung and esophageal SCC." (PMID 29262545, 2017). "A recombinant adenoviral vector Ad-ATF/SOX2 that expresses ATF/SOX2 suppressed SOX2 at the mRNA and protein levels in lung and esophageal SCC cells expressing SOX2." (PMID 29262545, 2017). "SOX2OT has also been identified in esophageal squamous cell carcinoma and concordant regulated with SOX2." (PMID 28033431, 2016).
esophageal squamous cell carcinoma (continued). "In lung and esophageal squamous cell carcinomas, Sox2 does in fact promote an embryonic stem cell gene expression signature, but the overall clinical impact of Sox2 expression is unresolved." (PMID 23326489, 2013). "While PIK3CA amplifications have previously been reported in HPV+ HNSCC, SOX2 has recently been proposed as the critical target of 3q gains observed at a high frequency in squamous lung cancer and in esophageal squamous cell carcinoma." (PMID 23718828, 2013). "Notably, the AKT inhibitor MK2206 exercised a pronounced impact on SOX2 expression within all evaluated SOX2-positive esophageal squamous cell carcinoma cell lines, notably hampering tumor sphere formation." (PMID 40034124, 2025). "Moreover, MTA3 downregulates SOX2OT, and the MTA3/SOX2-OT/SOX2 axis has been reported as a potential cancer stratification marker in human esophageal squamous cell carcinomas." (PMID 37519889, 2023). "But the role of SOX2OT in esophageal squamous cell carcinoma (ESCC) and the association between SOX2OT and SOX2 remain unclear." (PMID 29849506, 2018). "Next, we evaluated whether SOX2 expression could be suppressed by adenoviral mediated ATF/SOX2 (Ad-ATF/SOX2) induction in lung and esophageal SCC cells." (PMID 29262545, 2017). "The ATF suppressed MSH6 mRNA and protein expression in EBC2 cells, TE4 cells and TE10 cells suggesting that these genes might be downstream genes of SOX2 in lung and esophageal SCC." (PMID 29262545, 2017). "In human lung SCC and esophageal SCC sections, SOX2 expression was detected in more than 87.5% of sections suggesting that molecular targeting of SOX2 might be useful for treating SCC." (PMID 29262545, 2017). "Similarly, in esophageal squamous cell carcinomas, tumors in which more than 50% of the cells express SOX2 were correlated with increased lymphatic and vascular invasion, poor differentiation, and incomplete surgical resection." (PMID 28388544, 2017). "In addition, lnc-SOX2-1, also called SOX2-OT, can positively promote the transcription of SOX2 gene (one of the major regulators of pluripotency) and is dysregulated in esophageal squamous cell carcinoma, lung squamous cell carcinoma, and breast cancer." (PMID 26918340, 2016). "Consistently, most findings suggested that SOX2 expression could be a marker of poor prognosis in esophageal SCC, lung adenocarcinoma and oral tongue SCC." (PMID 28983346, 2015). "We previously reported that ΔNp63 or SOX2 may be effective in treating lung and esophageal SCC." (PMID 40871074, 2025). "We have previ-ously reported a significant upregulation of the lncRNA SOX2OT and its intronic cod-ing gene, SOX2, in esophageal squamous cell carcinoma (ESCC) tissue samples." (PMID 26862518, 2016). "An elevated expression of SOX2 has been correlated with poor prognosis of esophageal squamous cell carcinoma (ESCC)." (PMID 26370982, 2015). "For example, P63 regulates growth, invasion and metastasis of esophageal squamous cell carcinoma (ESCC) cells, and Sox2 functions as an amplified lineage-survival oncogene in ESCC." (PMID 26630178, 2015). "Indeed, a SOX2-targeting peptide, peptide 42 (sP42), significantly reduced esophageal squamous cell carcinoma (ESCC) KYSE450 and TE-1 proliferation, as well as migration and invasion." (PMID 38612911, 2024). "For example, the SEs of TP63, a lineage-specific master TF, are co-occupied with other CRC TFs (SOX2, KLF5, and TP63), and three SE constituents are required to transcribe TP63 as well as induce esophageal squamous cell carcinoma (ESCC) progression." (PMID 37501079, 2023). "Previous research demonstrates the interaction between SOX2 and KLF5 in the progression from normal tissue to esophageal squamous cell cancer (ESCC), suggesting a potential role in response to tissue injury." (PMID 37672481, 2023). "Emerging evidence indicates that SOX2 is an oncogene for esophageal squamous cell carcinoma (ESCC)." (PMID 37891174, 2023).